BECN1 (beclin 1)
Diseases named in the same sentence as BECN1 in open-access papers (continued):
Sharing a sentence is not in itself a finding about the gene and the disease.
endometriosis (continued). "In addition, Beclin-1 protein expression of eutopic endometria in patientswith endometriosis was negatively correlated with serum CA125 (r= -0.57, p<0.01)." (PMID 25780525, 2015). "Moreover, Beclin-1 was negatively correlated with serum CA-125 level and pelvic pain, suggesting that low expression of Beclin-1 could contribute to the development of endometriosis." (PMID 39596186, 2024). "Thus, GO and vitamin C induce apoptosis by BECN1 and decrease endometriosis." (PMID 35181729, 2022). "Although there are several reports on the role of autophagy‐related markers Beclin‐1 and LC3 in endometriosis, only a few studies have exploited in vitro and animal models to study the function of the Bnip3 molecule." (PMID 38645639, 2024). "Gene expression involved in ceramide synthesis (CERS1, SPTL1, and SMPD1) and autophagy (BECN1, LAMP, and PC3) were significantly higher in CCs with endometriosis according to FASN, BECN1, and LAMP protein expressions." (PMID 35992117, 2022). "In sum, the effects of gamma-oryzanol as a therapeutic agent to alleviate pathogenesis of endometriosis in rats were investigated by the protein level of ER-α, SF1, SIRT1, HO-1, LC3 and BECN1." (PMID 35181729, 2022). "Specifically, we found that transcript levels of beclin-1, ATG5, ATG4B, and ATG2B were significantly decreased in endometriotic lesions compared with uterine horns (from endometriosis-induced mice treated with PBS)." (PMID 26775710, 2016). "In particular, some early studies showed that ectopic endometrial cells presented low levels of Beclin-1 compared to endometrial cells of patients without endometriosis." (PMID 39596186, 2024). "Therefore, the present work assesses the effects of GO in rat models with surgically induced endometriosis, by evaluating the western blotting expression of ER-α, SF1, SIRT1, HO-1, LC3B, BECN1." (PMID 35181729, 2022). "Decreased expression of Beclin-1 and LC3 may be related to the occurrence and development of endometriosis." (PMID 35768796, 2022). "However, gene expression involved in ceramide synthesis (SPHK1, ASAH1, and SGPP1) and autophagy (BECN1, LAMP, and PC3) were significantly lower in MGCs with endometriosis, whereas CERS1 and UGCG expression increased." (PMID 35992117, 2022). "Beclin-1 and LC3 are downregulated in endometriosis and negatively correlated with clinical stage of endometriosis, and might be involved in the occurrence and development of endometriosis." (PMID 35768796, 2022). "In the endometriosis group, there were 59 cases of Beclin-1 and LC3 co-positivity, 17 cases of co-negativity, 3 cases of Beclin-1 positivity and LC3 negativity, and 5 cases of Beclin-1 negativity and LC3 positivity." (PMID 35768796, 2022). "However, the autophagic gene expression including BECN1, LAMP, and PC3 decreased in MGCs of endometriosis." (PMID 35992117, 2022). "In contrast to the observations in the lesions, we identified increased protein levels of beclin-1, LC3B, LC3A, and GABARAPL1 in uterine horns from endometriosis-induced mice compared with uterine horns from controls, with a concurrent increase in lipid droplets." (PMID 26775710, 2016). "In addition, a recent study suggests that decreased levels of Beclin-1 and LC3 may be related to the occurrence and development of endometriosis." (PMID 39596186, 2024). "However, the reports of Beclin-1 and LC3 in endometriosis are limited and controversial." (PMID 35768796, 2022). "Our results revealed that HMGB-1 was upregulated in ectopic endometrium, which was also positively correlated with inflammatory cytokines IL-6, TNF-α, and IL-1β, as well as autophagy-related protein beclin-1, suggesting that HMGB-1 might be involved in endometriosis." (PMID 33815277, 2021). "However, no studieson the expression of Beclin-1 in endometriosis haveyet been published." (PMID 25780525, 2015).
endometriosis (continued). "Moreover, the autophagic gene expression including BECN1, LAMP, and P62 increased significantly (with p < 0.05) in CCs of endometriosis (2.8-fold, 2.4-fold, and 2.6-fold, respectively) but not in MGCs of endometriosis." (PMID 35992117, 2022).
myocardial infarction (17 papers, 2018 to 2025). Gross necrosis of the myocardium, as a result of interruption of the blood supply to the area, as in coronary thrombosis. "This study revealed an augmentation of autophagy in the myocardium after myocardial infarction, as evidenced by the heightened expression of Beclin-1 in infarcted myocardium of rats." (PMID 40668529, 2025). "The immunoperoxidase color reaction analysis revealed high cytoplasmic immunoreactivity of Beclin-1 in untreated rats with myocardial infarction and treated with free liposomes." (PMID 40668529, 2025). "According to this report, activating α7 n Ach receptors at the initiator stage of reperfusion reduces myocardial infarct size by inhibiting Beclin-1 and cascading of signaling pathways against IR injury." (PMID 35425785, 2022). "The overexpression of myocardin augmented I/R-induced myocardial infarction sizes, which was inhibited by knockdown of Beclin 1, which indicates that myocardin activates autophagy-dependent cell death in cardiomyocytes during I/R injury." (PMID 29295976, 2018). "Zhang and He reported that lncRNA Malat1/mmu-miR-30a/Becn1 was involved in myocardial infarction." (PMID 36718444, 2023). "Beclin 1 knockdown by in vivo lentivirus infection inhibited autophagic cell death and salvaged myocardial infarction, while Beclin 1 overexpression abrogated the protective effect of hypertrophic preconditioning against myocardial infarction in I/R‐induced hearts." (PMID 33973685, 2021). "Moreover, the protective effect of hypertrophic preconditioning against myocardial infarction was mimicked by Beclin 1 knockdown, as shown by the reduced myocardial infarct size in lenti‐shBeclin‐infected mouse hearts." (PMID 33973685, 2021). "In contrast, Beclin 1 overexpression did not further promote I/R‐induced cardiomyocyte death but inhibited the protective effects of hypertrophic preconditioning against myocardial infarction in the I/R‐induced myocardium." (PMID 33973685, 2021).
diabetic nephropathy (16 papers, 2021 to 2026). "illustrated that curcumin modulates the accelerated cell death autophagy and apoptosis in diabetic nephropathy by increasing Beclin‐1 expression in mice." (PMID 39656379, 2024). "A diabetic nephropathy study reveals that phosphofurin acidic cluster sorting protein 2 (PACS2) binds to Beclin-1 and mediates the reorientation of Beclin-1 to MERCs, followed by the formation of mitophagosome." (PMID 36506093, 2022). "Beclin-1 and Bcl-2 are interrelated and their binding downregulates Beclin-1-mediated autophagy in diabetic nephropathy." (PMID 36003645, 2022). "In regard to potential biomarkers of autophagy, serum levels of beclin-1 were lower in patients with diabetic nephropathy than in control subjects." (PMID 39086958, 2022). "In diabetic nephropathy models, the up-regulation of miR-142-5p inhibits autophagy through up-regulation of BECN1." (PMID 33621197, 2021). "Furthermore, XIST protects podocytes against HG-induced damage, induces autophagy in podocytes, and suppresses the progression of diabetic nephropathy by regulating the miR-30d-5p/BECN1 axis." (PMID 38317244, 2024). "When 20 mg/kg resveratrol is used to interfere with diabetic nephropathy rat models, the autophagy markers Beclin-1 and LC3II in the resveratrol group were found significantly increased, while the creatinine clearance rate and 24 h urine protein quantification were decreased." (PMID 35449816, 2022). "Interestingly, in the diabetic group, serum beclin-1 showed an inverse correlation with the degree of albuminuria, consistent with the notion of autophagy dysfunction in late-stage diabetic nephropathy." (PMID 39086958, 2022). "Interestingly, a reduction in autophagy has been observed in the glomerular podocytes of mice with diabetic nephropathy, as evidenced by a significant decrease in the levels of Beclin 1, the ATG12-ATG5 conjugate, and LC3-II during the progression of diabetic nephropathy." (PMID 41439967, 2025).
Parkinson disease (16 papers, 2015 to 2025). A progressive degenerative disorder of the central nervous system characterized by loss of dopamine producing neurons in the substantia nigra and the presence of Lewy bodies in the substantia nigra and locus coeruleus. "Indeed, lentiviral delivery of beclin 1 in a mouse model of Parkinson’s Disease was shown to protect against the loss of neuronal markers, and in an AD model reduced amyloid pathology." (PMID 26692002, 2015). "Building upon these findings, it seems that the inhibition of autophagy—especially through the modulation of the Beclin-1-dependent pathway—holds a pivotal role in the neuroprotective effects of GA + ADSCs against Parkinson’s disease." (PMID 40999534, 2025). "There are also studies that found FOS could regulate autophagy in Parkinson's disease by increasing Becn1 expression." (PMID 38683127, 2024). "FOS has been reported as an essential factor in BECN1‐induced autophagy in Parkinson's disease." (PMID 38683127, 2024). "Transgenic mouse overexpressing beclin 1 could improve Parkinson’s disease (PD) progression by reducing α-synuclein aggregation through the enhancement of autophagy." (PMID 26999089, 2016). "siRNA-mediated knockdown (KD) of a modulator for autophagosome formation, ATG5, BECN1, or FIP200 inhibited autophagic flux and secretion, causing accumulation of Triton X-100-insoluble α-synuclein (α-syn), which is an aggregate-prone protein responsible for neuronal loss in Parkinson’s disease." (PMID 40683447, 2025). "In the A53T transgenic Parkinson’s mouse model (7-8 months), nilotinib (tyrosine kinase inhibitor) can enter the brain tissue and increase the autophagic clearance of α-Syn by upregulating Beclin-1, which protects dopaminergic neurons, thereby improving the motor function of PD mice." (PMID 33289703, 2020). "β-Asarone modulates the JNK/Bcl-2/Beclin-1 pathway, reducing JNK and p-JNK expression while increasing Bcl-2 and Beclin-1 levels in the striatum of 6-OHDA-induced Parkinson’s model rats, attenuating excessive autophagy." (PMID 40337511, 2025). "We have also shown that beclin-1 is upregulated in Ubisol-Q10- and E-ASH-treated animals using a Parkinson’s disease rat model, a neurodegenerative disorder with similar mechanisms to AD." (PMID 40871729, 2025). "β-Asarone inhibits the PERK/CHOP/Bcl-2/Beclin-1 pathway to alleviate ER stress and excessive autophagy in Parkinson’s disease rat models, reducing PERK phosphorylation, CHOP expression, and Beclin-1 release, while increasing Bcl-2 levels to inhibit autophagy." (PMID 40337511, 2025). "It has been shown that overexpression of miR-133a inhibits MPP+-induced autophagy (MAP1LC3A/MAP1LC3B, BECN1, NUP62) in a cellular model of Parkinson’s disease, and downregulation of miR-17-5p inhibits infarction-induced myocardial autophagy." (PMID 36324052, 2023). "Moreover, it could adjust the JNK/Bcl-2/Beclin 1 pathway and HSP70/MEF2D/Beclin 1 molecular chaperone-mediated autophagy pathway to reduce dopaminergic neurons injury induced by 6-OHDA in Parkinson's model rats." (PMID 33981351, 2021).
triple-negative breast carcinoma (16 papers, 2014 to 2024). An invasive breast carcinoma which is negative for expression of estrogen receptor (ER), progesterone receptor (PR), and human epidermal growth factor receptor 2 (HER2). "We reported that RCE induces G1 cell cycle arrest, senescence, and Beclin-1 dependent autophagy in triple-negative breast cancer cells through activation of the p38 and ERK1/2 pathways." (PMID 39139643, 2024). "Combination treatment inhibited autophagic flux by preventing Vps34/Beclin 1 complex formation and downregulating prenylated Rab7, an active form of the small GTPase necessary for autophagosome–lysosome fusion in triple-negative breast cancer cells." (PMID 37760764, 2023). "The present study examined the effects of tetrandrine suppressing proliferation, targeting LC3, p62, and Beclin-1 autophagy genes by inhibiting PI3K/AKT/mTOR signaling in Triple-negative breast cancer (TNBC) MDA-MB-231 cell." (PMID 30713576, 2019). "Immunohistochemical staining of consecutive sections of triple-negative breast cancer specimens revealed that tumor tissues expressed lower levels of BECN1, ATG16L1 and SQSTM1 than normal tissues." (PMID 28628113, 2017). "Also, we studied the relation between beclin-1 and Bcl-2 and their prognostic relevance in triple negative breast cancer." (PMID 36939902, 2023). "In triple-negative breast cancer, oleuropein inhibits cell migration and invasion induced by HGF through autophagy by upregulation of LC3-II/LC3-I and Beclin-1, as well as downregulation of p62." (PMID 39203892, 2024). "In TCGA data set, the gene expression of BECN1, ATG16L1 or SQSTM1 were markedly lower in triple-negative breast cancers (n=82) compared with other subtypes (n=391)." (PMID 28628113, 2017).
cardiomyopathy (15 papers, 2016 to 2025). A disease of the heart muscle or myocardium proper. "Reduced Beclin-1 expression and activity are linked to cancer, neurological disorders, cardiomyopathy, and aging." (PMID 40028479, 2025). "Previously, we reported that insufficient, maladaptive autophagy occurs during cardiomyopathy in endotoxemia, and promoting autophagy via Beclin-1 attenuates mitochondrial damage and improves cardiac performance at the same condition." (PMID 35265609, 2022). "We showed that nuclear translocation of p65 in cardiomyocytes, rather than a change in its phosphorylation level, increased the expression of beclin‐1, resulting in dysregulation of autophagy and cardiomyopathy in diabetic mice." (PMID 28643395, 2017). "Besides, FoxO3 modulated DOX cardiomyopathy associated with the autophagy‐related gene LC3B, p62 and Beclin 1, as well as mTOR signalling in vivo and in vitro." (PMID 40785055, 2025). "Immunoblot analysis showed that CHMP2B and BECLIN-1 protein expression were induced to variable degree in patient hearts IV.5 and IV.7 and in the other diseased hearts, indicating a similar response in cardiomyopathy of familial and idiopathic origin." (PMID 26753747, 2016). "Surprisingly, enhanced initiation of autophagy by over-expressing Beclin 1 Tg mice manifested an amplified cardiotoxic response, and Beclin 1 heterozygous deletion mice (Beclin 1+/−) showed protection from myocardial structural and functional changes in the chronic Dox cardiomyopathy model." (PMID 30765730, 2019). "In order to investigate the potential efficacy of autophagy in the development of DOX‐induced cardiomyopathy, we conducted an examination of the protein expression levels of several autophagy‐related proteins, namely LC3B, Beclin 1 and p62, in the myocardium of mice treated with DOX." (PMID 40785055, 2025). "One study reported that reduced the proteasomal degradation of Beclin-1 by HSPB6 exerted a cardioprotective effect, whereas another study found that the Beclin1 knockdown in cardiomyocytes exposed to high glucose in a model of type 2 diabetes-induced cardiomyopathy decreased apoptotic cell death." (PMID 40894905, 2025).
esophageal cancer (15 papers, 2014 to 2025). A primary or metastatic malignant neoplasm involving the esophagus. "Beyond LC3, other autophagy-related proteins, such as Beclin 1 and P62, have also been implicated in the progression of esophageal cancer." (PMID 40723786, 2025). "Here, we conducted a retrospective study on the histopathology of ESCC, investigated the expression of Beclin-1 and Bcl-2 proteins (both autophagy- and apoptosis-related) in esophageal cancer tissue, and analyzed the significance of these proteins for the prognosis of ESCC." (PMID 34257544, 2021). "Furthermore, knockdown of Beclin 1 and autophagy-related protein 7 (ATG7) expression levels, in OE19 and KYSE450 esophageal cancer cells, enhanced the effects of 5-fluorouracil (5-FU), a chemotherapeutic agent used to treat esophageal cancer." (PMID 25322694, 2015).
nasopharyngeal carcinoma (15 papers, 2013 to 2025). A carcinoma arising from the nasopharyngeal epithelium. "A randomized controlled study in patients with nasopharyngeal carcinoma receiving radiation and chemotherapy found that higher expression of Beclin 1 associated with lower overall survival and progression-free survival." (PMID 28881721, 2017). "By contrast, other authors have demonstrated that increased Beclin-1 expression is associated with relatively poor clinical results in pancreatic and nasopharyngeal cancer." (PMID 24282606, 2013). "However, other reports found higher expression of Beclin-1 associated with a poor prognosis in endometrial adenocarcinomas or nasopharyngeal carcinoma." (PMID 30849962, 2019). "In contrast, other groups discovered that increased Beclin-1 expression was correlated with unfavorable outcome in oral squamous cell carcinoma, nasopharyngeal carcinoma, and pancreatic ductal adenocarcinoma." (PMID 30107804, 2018). "A randomized controlled study on nasopharyngeal carcinoma patients receiving radiation and chemotherapy found that higher Beclin 1 expression related with worse prognosis." (PMID 28881721, 2017). "Contrary to these findings, in intrahepatic cholangiocarcinoma, ovarian epithelial carcinoma, and nasopharyngeal carcinoma, Beclin-1 expression was higher compared to corresponding normal tissue." (PMID 28070138, 2016). "For example, high Beclin-1 expression was considered to be a marker of poor prognosis in nasopharyngeal carcinoma and ovarian epithelial carcinoma." (PMID 28070138, 2016). "High Beclin-1 expression was connected to poor prognosis in endometrial adenocarcinoma and nasopharyngeal carcinoma in humans." (PMID 23578251, 2013). "Recently, Beclin 1 has been identified as a reliable biomarker in monitoring the prognosis for several tumors, such as brain, liver, gastric, colorectal, nasopharyngeal cancers and NK/T cell lymphoma." (PMID 23573264, 2013). "It was reported that in other types of human cancer, such as breast, prostate, liver and nasopharyngeal cancers, down-regulated expression of Beclin 1 was also frequently observed." (PMID 23573264, 2013). "Over-expression of Beclin-1 had been demonstrated in pancreatic and nasopharyngeal cancer." (PMID 33906303, 2021). "However, on the contrary, an elevated Beclin 1 expression was strongly correlated with poor OS and PFS in nasopharyngeal carcinoma (NPC)." (PMID 24260370, 2013).